RAD51 (RAD51 recombinase)
Diseases named in the same sentence as RAD51 in open-access papers (continued):
Sharing a sentence is not in itself a finding about the gene and the disease.
breast cancer (continued). "A functional polymorphism in the RAD51 gene, changing a guanine to cytosine at position 135 in its 5’ untranslated region, has been accused of modulating breast cancer risk by altering gene transcription." (PMID 26108708, 2015). "Many epidemiological studies have been carried out to examine the association between RAD51 135G > C polymorphism and the risk of breast cancer in different populations." (PMID 26108708, 2015). "Other studies have shown that the RAD51 135C variant allele was associated with an increased risk of female breast cancer." (PMID 24728564, 2015). "As it was mentioned in the Introduction above, the reports on the relationship between RAD51 G135C polymorphism and breast cancer incidence are suggest that the RAD51 135C variant allele was associated with an increased risk of female breast cancer." (PMID 24728564, 2015). "While germline mutations in RAD51C and RAD51D are associated with high ovarian cancer risk and RAD51B polymorphisms with breast cancer, the contribution of RAD51, XRCC3, and XRCC2 is more unclear." (PMID 25918678, 2015). "The present meta-analysis included 21236 cases and 19407 controls from twenty-eight studies on RAD51 135G > C polymorphism and breast cancer risk." (PMID 26108708, 2015). "Other experimental study confirms the significance RAD51 gene G135C polymorphism, regarding the risk of breast carcinoma." (PMID 25743260, 2015). "Elevated levels of RAD51 have been associated with increased invasiveness in breast cancer patients and have been demonstrated to be an independent prognostic marker of survival in non-small cell lung cancer patients." (PMID 24708616, 2014). "We observe that RAD51 is strongly associated with breast cancer pathology progression, high-grade tumours and metastasis." (PMID 24811120, 2014). "Previous meta-analyses were carried out to assess the effect of Rad51 G135C polymorphism on either the risk of breast cancer or acute leukemia." (PMID 24475258, 2014). "In the stratified analysis by cancer type, our results strongly indicated that Rad51 G135C polymorphism was associated with increased breast cancer risk while G172T polymorphism with decreased head and neck cancer risk." (PMID 24475258, 2014). "Using cell line, immunohistochemistry, in silico and animal model analysis we find that high RAD51 expression correlates with aggressive breast cancer and its loss retards metastasis." (PMID 24811120, 2014). "Our investigations suggested that the Rad51 G135C polymorphism is a candidate for susceptibility to overall cancers, especially to breast cancer, and that the G172T polymorphism is significantly associated with decreased risk of head and neck cancers." (PMID 24475258, 2014). "Meta-analysis of RAD51 135G>C polymorphism and breast cancer association according to BRCA1/BRCA2 mutation." (PMID 24040396, 2013). "Some recent meta-analysis only analyzed RAD51 135G>C polymorphism with breast cancer risk, but the results were also inconsistent." (PMID 24040396, 2013). "Recent meta-analysis only analyzed RAD51 135G>C polymorphism with breast cancer risk, but the results were also inconsistent." (PMID 24040396, 2013). "This meta-analysis suggests that RAD51 variant 135C homozygote is associated with elevated breast cancer risk among BRCA2 mutation carriers." (PMID 24040396, 2013). "These RAD51-dependent processes are facilitated by many accessory factors including the breast cancer susceptibility gene product BRCA2." (PMID 23341130, 2013). "In conclusion, this meta-analysis suggests that RAD51 variant 135C homozygote is associated with elevated breast cancer risk among BRCA2 mutation carriers." (PMID 24040396, 2013). "We identified 12 distinct rare RAD51 variants in 0.75% (10/1.330) of early-onset breast cancer cases and 0.8% (9/1.123) of controls, all but one of them novel." (PMID 23300655, 2012).
breast cancer (continued). "In this study, the K1440E mutation, found in the hBRC3 of human breast cancer patients, reduced the interaction of the mutant protein with cRAD51 and hRAD51 and reduced or abolished the ability of RAD51 to self-associate." (PMID 23071527, 2012). "Previous structural analyses of cancer-associated mutations affecting BRC repeats showed that the weakening of RAD51 affinity in the case of even 1 repeat is adequate to increase breast cancer susceptibility." (PMID 23071527, 2012). "Since previous studies were based on very small numbers of patients, a larger population-based study to investigate the contribution and frequency spectrum of RAD51 germline variants to breast cancer susceptibility is warranted." (PMID 23300655, 2012). "Previous structural analyses of cancer-associated mutations affecting the BRC repeats have shown that the weakening of RAD51's affinity for even 1 repeat is sufficient to increase breast cancer susceptibility." (PMID 23071527, 2012). "Altogether, our data suggest that RAD51 tolerates so little dysfunctional sequence variation that rare variants in the gene contribute little, if anything, to breast cancer susceptibility." (PMID 23300655, 2012). "The results from our limited analysis of breast cancer tissues, including one from a patient with the M1775R mutation, are in line with our in vitro findings and the notion that RAD51 and RPA foci levels are elevated in cells that express M1775R." (PMID 21666281, 2011). "Although, there have been some reports of Rad51 haplotypes associated risk in high-risk families and with sporadic breast cancer risk, these haplotypes are composed only of SNPs in the Rad51 putative promoter, introns, or the 3' un-translated region." (PMID 21708019, 2011). "One study examined the effects of a Rad51 genotypes in BRCA1/2 carriers and reported that Rad51 135G>C genotype association with breast cancer risk was greater in BRCA1 carriers with truncating mutations (i.e. 185delAG)." (PMID 21708019, 2011). "These include Rad52, the human Rad51 paralogs Rad51B, Rad51C, Rad51D, Xrcc2, and Xrcc3, and breast cancer susceptibility gene Brca2." (PMID 21129202, 2010). "The aim of the present study was to attempt to elucidate a role for RAD51 as a high-risk breast cancer predisposition gene using DHPLC and well-characterised non-BRCA1/2 familial breast cancer patients." (PMID 16762046, 2006). "The RAD51 gene region has been shown to exhibit loss of heterozygosity in breast tumours, and deregulated RAD51 expression in breast cancer patients has also been reported." (PMID 16762046, 2006). "There has been one report of a missense variant in RAD51 being detected in a breast cancer population to date." (PMID 16762046, 2006). "With regard to RAD51 mutations and cancer predisposition, three studies have used various mutation detection methodologies to screen RAD51 in breast cancer patients." (PMID 16762046, 2006). "RAD51 interacts directly or indirectly with a number of proteins implicated in breast cancer, such as BRCA1 and BRCA2." (PMID 16762046, 2006). "A single-nucleotide polymorphism (SNP), RAD51-135g → c, in the 5′ untranslated region of the gene has been found to elevate breast cancer (BC) risk among BRCA2 carriers." (PMID 15138485, 2004). "In addition, the formation of RAD51 foci has been linked to resistance to PARPis in breast cancer patients carrying germline BRCA mutations." (PMID 41537447, 2026). "RAD51 was also shown to be a marker of resistance to PARPi in BRCA-mutated breast cancer, and depletion of RAD51 via RNAi could re-sensitize cancer cells to PARP inhibition." (PMID 40782795, 2025).
breast cancer (continued). "Pathogenic RAD51C variants contribute to breast cancer risk, and elevated RAD51 levels in cell lines and primary tumors suggest that driving the HR pathway beyond physiological levels may also play a role in genomic instability and hence tumor progression." (PMID 39334297, 2024). "Moreover, PARP inhibitor (PARPi) benefit was observed in prostate cancer and breast cancer with loss of RAD51 foci." (PMID 38607586, 2024). "Meta-analysis of the Rad51 G172T polymorphism on the risk of breast cancer." (PMID 36761956, 2023). "In conclusion, XRCC3 and RAD51 polymorphisms might contribute to RT adverse events in early HER2-positive breast cancer patients." (PMID 36139526, 2022). "Even though data regarding the influence of genetic variability on the occurrence of a new tumor are scarce, there are many reports in the literature that DNA repair genes, including XRCC3 and RAD51, are associated with the development of breast cancer and other cancer types." (PMID 36139526, 2022). "Several meta-analyses highlighted the RAD51 G135C variant could function as a potential candidate biomarker for various cancers, particularly breast cancer." (PMID 35061678, 2022). "One explanation may reside in the capacity of bCSCs from BRCA-mutated breast cancers to maintain a functional RAD51 activity avoiding the triggering of the synthetic lethality." (PMID 35110528, 2022). "Moreover, RAD51 foci formation correlates with resistance to PARP inhibitor in breast cancer patients with germline BRCA mutations." (PMID 35646698, 2022). "In addition, we found high-level Rad51 was associated with tumorigenesis and poor prognosis in breast cancer patients." (PMID 33842359, 2021). "Associations of Rad51/Xrcc3 SNP combinations with breast cancer." (PMID 31905201, 2020). "Treatment with melatonin before radiation caused a significantly higher decrease in RAD51 and DNA-protein kinase mRNA expression and sensitizes human breast cancer cells to ionizing radiation by reducing their proliferation, promoting cell-cycle arrest and decreasing the effectiveness of DNA repair." (PMID 32726912, 2020). "This may be explained by the fact that the loss of RAD51 may only be biologically relevant in the setting of demonstrated DNA damage (gH2AX) in the S–G2 phase (geminin), as recently published for breast cancer." (PMID 32192091, 2020). "Several studies have shown that RAD51 genetic polymorphisms may contribute to RAD51 expression differences among individuals, leading to the development of breast cancer." (PMID 32316696, 2020). "Thirdly, RAD51 was found to be structurally compatible with AIs, which may cause dysfunction of AIs and then AI-resistance of breast cancer." (PMID 31506496, 2019). "Interestingly, loss of SIM2s was shown to result in failure of RAD51 to localize to sites of replication stress in both breast cancer cell lines and primary mammary epithelial cells." (PMID 31775907, 2019). "Moreover, we also found that a high expression of RAD51 was associated with poor survival outcome of patients with breast cancer or ER-positive breast cancer (P < 0.01, P < 0.05)." (PMID 31506496, 2019). "Theoretically, PARP inhibitors may have an effect on breast cancers with deficiency of HRR pathway including a dysregulation of BRCA2/RAD51 machinery." (PMID 31506496, 2019). "R150Q is associated with familial breast cancer and G135C is associated esophageal cancer and breast cancer while RAD51 G127T might protect against head and neck cancer." (PMID 31435521, 2018). "Finally, we demonstrated that the RAD51 assay is feasible in formalin‐fixed paraffin‐embedded (FFPE) routine breast cancer samples and accurately classified as HRR‐deficient all the PALB2‐related tumors." (PMID 30377213, 2018). "Elevated levels of RAD51 are associated with breast cancer and chronic myeloid leukemia (CML)." (PMID 31435521, 2018).
breast cancer (continued). "Low quantities of Rad51 foci measured by immunofluorescence in post-chemotherapy biopsies were also associated with pathologic complete responses to anthracycline-based chemotherapy in sporadic primary breast cancers." (PMID 29340034, 2017). "Therefore mutations in three consecutive residues in a single motif of RAD51 protein are associated with breast cancer." (PMID 25539919, 2015). "Furthermore, the RAD51 missense mutation was later also detected once among 1330 breasts cancer cases as well as once among 1123 controls." (PMID 25918678, 2015). "Low quantities of RAD51 foci measured by IF in post-chemotherapy biopsies were associated with pathologic complete response to anthracycline-based chemotherapy in sporadic primary breast cancers." (PMID 26198537, 2015). "Thus, compromised DNA repair system as a result of faulty RAD51 protein increases breast cancer risk." (PMID 26108708, 2015). "Finally, we examined the expression of genes associated with the RAD51-TODRA regulatory pathway in breast cancer tumors." (PMID 26230935, 2015). "We conclude that RAD51 135G > C substitution may serve as a useful marker for screening of breast cancer risk; Nevertheless, its use may be restricted to the Caucasian populations." (PMID 26108708, 2015). "Several studies reported that RAD51 overexpression was associated with poor prognosis in various cancers such as non-small-cell lung carcinoma, head cancers, esophageal squamous cell carcinoma, breast cancer, melanoma, and CRC." (PMID 26046797, 2015). "Our results suggested that the Rad51 G135C polymorphism is a candidate for susceptibility to overall cancers, especially to breast cancer, and that the Rad51 G172T might play a protective role in the development of head and neck cancer." (PMID 24475258, 2014). "XRCC3 and RAD51 were significantly associated with clinicopathological factors and they might play important roles in the development and progress of breast cancer." (PMID 23977219, 2013). "DACH1 repressed p21CIP1 and induced RAD51, an association found in basal breast cancer." (PMID 23798621, 2013). "In both dogs and humans, these mutations might be involved in mammary tumors as a result of their effect on the regulation of RAD51 recruitment." (PMID 23071527, 2012). "Stratified analyses of the RAD51 −135G/C SNP on breast cancer risk in the BCFR." (PMID 23300655, 2012). "We thus postulated that RAD51 could harbor rare germline mutations that confer increased risk of breast cancer." (PMID 23300655, 2012). "In order to identify SNPs and haplotypes in BRCA1and Rad51 that might affect familial and sporadic breast cancer risk, we conducted a study of genotype-phenotype relationships." (PMID 21708019, 2011). "Our results provide evidence that deficient DNA repair may be a biomarker to identify higher-risk individuals in BRCA1 families, and provides an a priori hypothesis for further studies of BRCA1 and RAD51 SNPs in familial breast cancer risk." (PMID 21708019, 2011). "Because SNPs in the 5'-UTR can exert regulatory functions in some genes with implications for breast cancer risk, e.g. in RAD51, we assessed the frequency of the rare allele of rs4252668 in an additional set of 133 patients with bilateral breast cancer and 136 population controls." (PMID 18279506, 2008). "It proves that germline mutations in the RAD51 gene may modulate the risk of breast cancer." (PMID 36761956, 2023). "In addition, elevated RAD51 protein expression has been found to be associated with poor survival in a variety of tumors, including ovarian cancers, lung cancers, pancreatic cancers, esophageal cancers, neuroblastoma, and breast cancers." (PMID 37798649, 2023). "Increased RAD51 levels may contribute to tumorigenesis, and accordingly we found that elevated RAD51 levels are associated with young age at breast cancer onset, higher tumor grade and characteristics of aggressive tumors (e.g. lack of hormone receptor expression and HER2 amplification)." (PMID 26230935, 2015).
breast cancer (continued). "Here, the authors tested a newly developed mass cytometry panel comprising biomarkers such as γH2AX and RAD51 in longitudinally monitored metastatic breast cancer patients." (PMID 40456663, 2025). "In fact, we discovered these genes to be enriched for RAD51 in the context of the breast cancer cell line MCF7, with intact BRCA." (PMID 41350536, 2025). "To investigate this, we utilized ChIP-seq data of the HR DNA repair protein RAD51 in MCF7 breast cancer cells." (PMID 41350536, 2025). "We next examined the role of the BCKDK/p‐RNF8/RAD51 axis in contributing to therapy resistance in breast cancer." (PMID 40298908, 2025). "For example, miR-449a has been reported to target EME1 and downregulate BRCA2 and RAD51 in breast cancer, while miR-146 targets and/or downregulates FANCM and BRCA1 in cervical, gastric, and breast cancer cells." (PMID 41008855, 2025). "RAD51 is frequently overexpressed in breast cancer and plays key roles in tumor cell development and survival." (PMID 40949156, 2025). "Studies indicate that mutations occurring within exon 27 disrupt the binding between BRCA2 and RAD51 C-terminal domain resulting in embryonic damage and significantly reduced lifespan based on mouse models of breast cancer." (PMID 40612353, 2025). "In breast cancer, lower levels of RAD51 positively correlate with responses to neoadjuvant chemotherapy or PARPi treatment." (PMID 40830526, 2025). "Accordingly, RAD51 inhibition sensitized chemoresistant breast cancer cells to doxorubicin and docetaxel and increased the sensitivity of breast cancer cells to adriamycin and cisplatin." (PMID 39863855, 2025). "Similar findings have been reported in breast cancer, where genes like RAD51 and CHEK2 contribute to radiation sensitivity." (PMID 40652278, 2025). "By examining DNA damage repair‐associated factors, we observed a large decrease in RAD51 protein levels following BCKDK knockdown, while RAD51 levels increased upon RNF8 knockdown in breast cancer cell lines." (PMID 40298908, 2025). "Western blot analysis revealed that RAD51 ubiquitination levels were increased in BCKDK‐silenced breast cancer cells, an effect that was restored with RNF8 knockdown." (PMID 40298908, 2025). "Another paralog of RAD51 is XRCC2, encoded by the XRCC2 gene, which has a disputable relationship to breast cancer risk." (PMID 39684352, 2024). "Treating MCF-7 and MDA-MB-468 breast cancer cells with berberine at a concentration of 15 μM and subjecting them to various doses of X-rays (ranging from 1 to 4 Gy), resulted in a decrease in RAD51 protein levels compared to control cells." (PMID 38993643, 2024). "Berberine enhances radiation sensitivity in irradiated breast cancer cells by regulating cell cycle arrest at the G2/M phase and downregulating RAD51 protein." (PMID 38993643, 2024). "As a comparison, we included the analysis of RAD51 foci in primary tumor samples from patients with untreated breast cancer with germline PVs in BRCA1, BRCA2, and PALB2, which showed a high prevalence of HRD (92.2% [95 of 103]), as expected." (PMID 38648056, 2024). "The PTEN protein promotes DNA repair through RAD51-dependent homologous recombination, and PTEN-deficient breast cancer cells are sensitive to olaparib, a RI-1 inhibitor." (PMID 39334297, 2024). "First described in primary cultures of ovarian tumor cells, RAD51 IF staining has been primarily studied in breast cancer." (PMID 38725623, 2024). "Several studies have demonstrated that loss of HP1α impairs the recruitment of RAD51 and BRCA1 (breast cancer 1, early onset), two HR proteins, that delay DSB repair after irradiation, and lead to radiosensitivity." (PMID 39414799, 2024).